RNU6-664P (RNA, U6 small nuclear 664, pseudogene)
Gene: Small nuclear RNA gene on chromosome 2 (207,680,533 to 207,680,639, reverse strand). Ensembl gene ENSG00000199251.
Homologues: Orthologues: chimpanzee U6 (98% identical), macaque U6 (97% identical), guinea pig U6 (81% identical), dog U6 (80% identical). Paralogues in human: RNU6-698P (93% identical), RNU6-140P (92% identical), RNU6-1316P (91% identical), RNU6-38P (91% identical), RNU6-641P (91% identical), RNU6-214P (90% identical), RNU6-25P (90% identical), RNU6-338P (90% identical), RNU6-33P (90% identical), RNU6-434P (90% identical), RNU6-49P (90% identical), RNU6-891P (90% identical), and 1287 more.